MUC1 (mucin 1, cell surface associated)
Diseases named in the same sentence as MUC1 in open-access papers (continued):
Sharing a sentence is not in itself a finding about the gene and the disease.
breast carcinoma (continued). "First, though MMP-2 levels are increased in mouse mammary tumors, its expression is confined to the stroma, suggesting that increased MMP2 transcription after loss of the epithelium-specific MUC1 might reflect a shift towards a more mesenchymal phenotype." (PMID 16846534, 2006). "Second, MMP-2 levels are increased by overexpression of erbB2; previous studies have shown that erbB2 and Muc1 expression are mutually exclusive in mammary tumors, implying that MMP2 might be part of a transcriptional profile linked to low MUC1 levels." (PMID 16846534, 2006). "Researchers are now investigating the potential of DC vaccines in treating breast cancer, particularly in patients with specific tumor antigens, such as HER2, mucin 1 (MUC1), or other tumor-associated markers that could be targeted through dendritic cell-based strategies." (PMID 40333213, 2025). "The NCT04020575 phase 1/2 trial is a first-in-human study that aims to evaluate MUC1-targeting CAR-T cells in patients with metastatic breast cancer (BC)." (PMID 40675157, 2025). "In addition, it would also be interesting to investigate the other promoters, especially those described to be mostly breast cancer tissue-specific, such as ErbB2 and MUC1, or a BCSC-specific promoter, like MDR, to further enhance the therapeutic potential of OAd expressing hNIS." (PMID 38675909, 2024). "Therefore, we evaluated whether sulfated MUC1 was secreted into the blood of patients with breast cancer." (PMID 39337716, 2024). "Thus, we believe that evaluation of MUC1 localization by immunohistochemical staining has the potential to be a simple and cost-effective option to estimate the aggressiveness of luminal-type breast cancer." (PMID 37002293, 2023). "In breast cancer MCF-7 cells, the results of cell viability were basically in line with above analysis, and BAG pretreatment contributed to higher susceptibility towards these drugs that was only found in WT cells, supporting that BAG induced sensitiveness specifically relied on MUC1 expression." (PMID 35970845, 2022). "Moreover, contrary to previous studies on women with sporadic breast cancer, no increase in MUC1 IgG antibody levels was found in women at high genetic risk of breast cancer." (PMID 36451832, 2022). "In addition, mucin-related tumor markers have been widely used in clinical practice, for example, MUC16 (CA125) has been widely used as a marker for ovarian cancer; SLea (also called CA19-9) is a marker for pancreatic cancer; MUC1 (CA153) is a biomarker for breast cancer." (PMID 36429094, 2022). "The early work on aberrant MUC1 expression in breast cancer was extended by studies in other types of adenocarcinomas and squamous cell carcinomas, as well as hematologic malignancies, that continue to shed light on the involvement of MUC1 in cancer initiation and progression." (PMID 36230728, 2022). "We hypothesized that the unique radiofluorinated MUC1-conjugated folic acid (FA) hybrid peptide targeting both the MUC1 and folate receptors would be superior in breast cancer targeting to the radiofluorinated MUC1 monomeric peptide or folate targeting only the folate or folate receptors." (PMID 33738611, 2021). "Moreover, MUC1/Y aptamer inhibited the tumour growth of breast cancer cells in vivo." (PMID 34452200, 2021). "Along these lines, MUC1 is highly expressed in the lactating mammary gland, which (i) occurs in association with suppression of the EMT program to preserve epithelial integrity and differentiation and (ii) upon remodeling during involution rarely progresses to breast cancer." (PMID 31953400, 2020). "Finally, to determine whether these proteins may be present in the TME, we assessed for seven top validated factors, and MUC1, in the interstitial fluid of fresh breast cancers, finding all factors, to varying levels, in all tumours tested." (PMID 33149188, 2020).
breast carcinoma (continued). "Therefore, we hypothesized that this sequence could be useful to design a synthetic MUC1 peptide derived from the tumor-antigen for targeting MUC1-positive breast carcinoma." (PMID 31470531, 2019). "Thus, MUC1 Apt can be used for targeted drug delivery to breast cancer cells." (PMID 30041514, 2019). "Thus, we analyzed whether the GGSK-1/30 mAb was applicable as a biomolecular imaging agent selectively binding to (TA)MUC1 in a preclinical breast cancer mouse model." (PMID 31588183, 2019). "Since many types of breast cancer cells express high levels of Mucin-1 (MUC1) on their cell surfaces, the main purpose of imaging is utilizing SPIONs conjugated to monoclonal antibody (C595) that bind to the MUC1, as contrast enhancement for detecting breast cancer cells." (PMID 28601058, 2017). "Furthermore, T-cells from GM+R848+LPS conditioned PBMC driven by either SEA2 or SEA1 long peptides not only specifically recognized one or both of these sensitizing peptides at restimulation, but also preferentially lysed the HLA-A2.1+ human breast cancer line MDA-MB-231 transduced to express MUC1." (PMID 27974697, 2017). "Breast cancer targeting using CAR technology has been well documented with studies reporting the generation of CAR for breast cancer-associated tumour antigens such as carbonic anhydrase IX, ERBB2, mesothelin, EGFR variant III (EGFRvIII), carcinoembryonic antigen (CEA), and Mucin-1 (MUC-1)." (PMID 28885562, 2017). "Notably, ezrin has been shown to colocalize with MUC1 in breast carcinomas." (PMID 28588132, 2017). "However, in breast cancer cells, Muc1 was shown to promote c-Met-driven migration and scattering through regulation of c-Met mRNA expression levels, suggesting that tissue conditional aspects determine the consequences of the relationship between Muc1 and c-Met." (PMID 28536399, 2015). "In addition, MUC1 interacts with β-catenin, promoting invasion of breast cancer." (PMID 25124875, 2014). "However, when looking at the histopathological grading, multicentric/multifocal carcinomas showed a statistically significant decrease in staining with increased histology grade (p = 0.027) which was in contrast to the MUC1 expression in unifocal breast cancer of different grade." (PMID 23890049, 2013). "MUC1, which is overexpressed in breast cancer, may contain Lewis y." (PMID 19715603, 2009). "Moreover, the bulk of viral progeny produced by the MUC-1-positive breast cancer cell line T47D was found in the media, indicating that viral infection of T47D cells with the Ad5AMUCH_RSV-NIS CRAd resulted in cell lysis and subsequent release of infectious viral particles." (PMID 19635153, 2009). "However, the number of patients analyzed in our study is far too small to exclude that MUC1-expressing cells might have clinical relevance in certain subsets of breast cancer." (PMID 19549321, 2009). "However, Western blot analysis of H9 hESCs revealed a 20 kD Anti-MUC1* reactive species that co-migrated with the MUC1 cleavage product from T47D breast cancer cells and with transfected MUC1*1110, that contains only forty-five amino acids of the extracellular domain." (PMID 18833326, 2008). "We have developed sensitive assays for cytokeratin (K) 8, 16, 19, stromelysin 3 (ST3), MUC1 and maspin mRNAs using reverse transcription polymerase chain reaction (RT-PCR) and used these to assess lymph node status in patients undergoing surgery for breast cancer." (PMID 10471055, 1999). "Mice inoculated with 4T1 mammary carcinoma cells had enhanced IFN-γ secretion and MUC1-specific CD8+ T cell killing when immunized with 10 μg of a MUC1 mRNA nanovaccine encapsulated in lipid/calcium/phosphate nanoparticles (LCP) compared to mRNA or LCP alone." (PMID 41012179, 2025).
breast carcinoma (continued). "Yet, despite encouraging preclinical results in breast cancer models targeting HER2, MUC1, or mesothelin, single-target CAR-T cells have demonstrated minimal clinical efficacy in solid tumors, including breast cancer, with objective response rates below 13%." (PMID 41348261, 2025). "It is known that aberrant overexpression of the MUC1 and HER2 receptor is often observed in breast cancer." (PMID 40699615, 2025). "Low amounts of common antigens investigated for breast cancer, including HER2, MUC1, and EGFR, are also present in normal tissues, raising the possibility of unintentional CAR-T-cell activation and toxicities such “on-target, off-tumor” consequences." (PMID 39755633, 2025). "The content of MUC1 antigens (CA15-3, CA27.29, and MCA) statistically significantly decreased in the luminal B(+) subtype of breast cancer." (PMID 40699615, 2025). "The EBV LMP1 protein contributes to upregulation of MUC1 expression in (i) KH-1/2 cells derived from fusions of KR-4 lymphoblastoid and HeLa cells, and (ii) EBV-infected breast cancer cells." (PMID 40764753, 2025). "Till date, no one tried combination of tetraethylenepentamine modified bis-MPA dendrimer, MUC1, PEG and survivin siRNA for breast cancer therapy." (PMID 38699430, 2024). "The cancer antigen 15-3 assay (CA15-3) has been widely used for the detection of breast cancer recurrence, and the epitope detected in the CA15-3 assay is an extracellular domain of MUC1." (PMID 39337716, 2024). "Other mucins, such as MUC1, MUC2 and MUC5AC, are rarely expressed in normal tissues but are expressed in the early stages of lung cancer, breast cancer, and colon cancer." (PMID 38702644, 2024). "MUC1 and vascular endothelial growth factor (VEGF) expression in human breast cancer are highly correlated, promoting the synthesis and secretion of VEGF through the AKT signaling pathway." (PMID 38164273, 2024). "A MUC-1/HER-2 chimeric protein induced cellular and humoral immune response in a murine breast cancer model." (PMID 38474142, 2024). "In the case of breast cancer, dual targeting of HER2 and MUC1 demonstrated efficacy in an in vitro model." (PMID 39835140, 2024). "As aberrant expression of EGFR and MUC1 has been reported in various epithelial tumors, we carried out IHC experiments on LUAD, CRC and breast cancer tissues." (PMID 39664199, 2024). "MUC1 and MUC16, as key biomarkers in gynecological tumors, particularly ovarian and breast cancers, have attracted significant attention for their roles and potential in tumor immunotherapy." (PMID 38361923, 2024). "Cancer antigen 125 (CA125) for ovarian cancer as well as cancer antigen 15–3 (CA15-3) and cancer antigen 27–29 (CA27-29) for breast cancer are based on mucin proteins mucin-16 (MUC16) and mucin-1 (MUC1), respectively." (PMID 38515194, 2024). "A correlation was shown between the increased expression of MUC1 mRNA and the level of estrogen and progesterone in MCF7 and ZR75-1 breast cancer cell lines." (PMID 39456554, 2024). "Cancer antigen 15-3 (CA15-3), a member of the mucin glycoprotein family (MUC1), is widely used as a tumor marker in breast cancer patient management." (PMID 39742378, 2024). "The impact of MUC1 and MUC16 on the progression of breast cancer has been extensively studied and confirmed." (PMID 38361923, 2024). "An increase in the level of MUC1 CA 15-3, CA 27.29, and MCA was observed only for luminal A breast cancer." (PMID 39456554, 2024). "This suggests that the modification of the nanoparticles with the S2.2 aptamer, which has a affinity for MUC-1, increased the effectiveness of the PTX delivery system to MCF-7 breast cancer cells, resulting in increased MCF-7 cell death." (PMID 38675202, 2024). "Despite the fact that the MUC1 level in the HER2(+) subgroup is maximally reduced, we observed relative increases in advanced breast cancer stages, as well as in cases of low cell differentiation and high proliferative activity index." (PMID 39456554, 2024).
breast carcinoma (continued). "MUC1 is highly expressed in luminal subtypes, particularly luminal A and HER2-enriched breast cancers." (PMID 39671082, 2024). "Previous reports highlighted the use of different promoters for breast cancer virotherapy such as hTERT, MDR, mucin-1 (MUC1), hypoxia-responsive, estrogen-responsive, surviving, L-plastin, and Cyclooxygenase-2 (Cox-2)." (PMID 38675909, 2024). "Further, tumor cells selected by brain endothelium adhesion expressed higher levels of MUC1, VCAM1, and VLA-4, which were relevant to breast cancer brain metastasis." (PMID 37108248, 2023). "These include MUC1 and CD44 for breast cancer, CD44 for colon cancer, or CD34 for leukemia, although one cell is not restricted to only one carrier." (PMID 37915564, 2023). "Breast cancer cells express multiple types of CAM, including PSGL-1, CD24, sLex, MUC1, CD 44, MUC1, LFA-1 (integrin αLβ2), VLA-4 (integrin α4β1), and ALCAM, whereas melanoma and lung cancer have limited CAM expression." (PMID 37190188, 2023). "Rahn and co-workers evaluated tumors in 71 breast cancer patients by immunohistochemical staining with mAb B27.29, specific for an epitope PDTRPAP in the tandem repeat of MUC1, and found that tumors with poor staining in the cytoplasm had a good prognosis." (PMID 37002293, 2023). "MUC1 interacts with and helps boost PI3K/AKT, ERK, and receptor tyrosine kinases (RTKs) to promote breast cancer progression." (PMID 36405816, 2023). "Previously, we demonstrated that F3 had anti-metastatic activity in breast cancer by reducing the expression of N-cadherin, vimentin, MMP-9, MUC1, Twist, and VEGF, while increasing the expression of E-cadherin." (PMID 37259304, 2023). "CDH1, CST6, MUC1 and SCNN1A genes, all reported to be aberrantly hypermethylated in breast cancer, were down-regulated in both MDA-MB-231 and Hs578T GLO1-depleted breast cancer cells when compared with control." (PMID 36998085, 2023). "A novel co-stimulatory receptor composed of the scFv of the TR2 mAb combined with a 4-1BB endodomain successfully protected anti-MUC1 CAR T-cells from MDSC immunosuppression and promoted superior anti-tumor activity in breast cancer models." (PMID 38201551, 2023). "Particularly, the E-selectin interacts with its ligands expressed on breast cancer cells, including platelet selectin glycoprotein ligand-1 (PSGL-1), cluster of differentiation 24 (CD24), sialyl-Lewis X (sLex), and mucin-1 (MUC1) to allow rolling." (PMID 37190188, 2023). "MUC1 degrades ATAD3A by inducing ubiquitination and promotes mitophagy in a Pink1-dependent manner, thereby inducing breast cancer progression." (PMID 36831455, 2023). "We previously demonstrated that the WAP-TGFα transgenic mouse model is sensitive to knockout of the retrograde driver, Muc1, highlighting its use as a model of EGFR-dependent breast cancer." (PMID 36253541, 2023). "Clinical trials are underway to assess the effects of CAR-T cell therapy for treating breast cancer, including CAR-T cells recognizing epithelial cell adhesion molecule (EpCAM) (NCT02915445), cleaved MUC1 (NCT04020575, NCT02792114), and ROR1 (NCT05274451)." (PMID 36387071, 2022). "Mucin 1 (MUC1) is expressed in more than 90% of breast cancers, making it the most relevant and significant antigen for breast cancer targeting." (PMID 36153626, 2022). "In this study, we have generated CAR T cells targeting mucin-1 (MUC1), which is an aberrantly glycosylated antigen overexpressed on breast cancer cells." (PMID 36457849, 2022). "Over-expression of transmembrane mucin proteins such as MUC1 and growth factor like HER2 in breast cancer are sufficiently documented and our results on them support such findings." (PMID 36210467, 2022).
breast carcinoma (continued). "For the treatment of breast cancer, preclinical studies are ongoing to examine the effects of CAR-T cell therapy on various tumor specific antigens including mucin 1 (MUC1), HER2, Lewis Y, mesothelin, and folate receptor alpha (FR-α)." (PMID 36387071, 2022). "In conclusion, a novel vaccine for breast cancer was developed with three components: a small-molecule TLR7 agonist (SZU251), an MUC1-related peptide (MUC1) and an aluminum adjuvant (Al)." (PMID 36499455, 2022). "This preclinical evaluation provides evidence for the selection of a particular MUC1-targeted CAR construct for further in vivo and clinical studies of breast cancer treatment." (PMID 36457849, 2022). "Reliably, an inverse correlation between MUC1 and ATAD3A was found in tumor tissues of breast cancer patients." (PMID 36289190, 2022). "To examine the clinical relevance of MUC1 and ATAD3A in breast cancers, we collected 110 samples from breast cancer patients." (PMID 36289190, 2022). "To assess the function of MUC1-induced mitophagy, we stimulated cells for 2 h with CCCP to activate mitophagy and examined breast cancer cell proliferation." (PMID 36289190, 2022). "Our data indicate that cosuppression of mitophagy and MUC1 by combining Mdivi-1 and GO203 remarkably eliminated the malignancy characteristics of breast cancer cells in vitro and in vivo." (PMID 36289190, 2022). "Mucin-1 (MUC1), a kind of O-glycosylated transmembrane glycoprotein, was the potential biomarker in breast cancer, lung adenocarcinoma, and colorectal adenocarcinoma." (PMID 36405691, 2022). "Consistently, MUC1 and ATAD3A protein levels present an inverse relationship in tumor tissues of breast cancer patients." (PMID 36289190, 2022). "In breast cancer, bispecific CAR-T cells targeting HER2 and MUC1 were successfully constructed and exhibited cytotoxic activities." (PMID 35414783, 2022). "There was higher expression of IL6, MCP1, BCL2, luminal cytokeratins, MUC1, BRCA1, BRCA2, CEA and CA 15-3 in older women with primary breast cancer compared to younger women." (PMID 34165702, 2021). "The two TAAs mucin-1 (MUC1) and survivin were selected as targets for breast cancer immunotherapy due to their overexpression in approximately 90% of breast cancers." (PMID 34066318, 2021). "Overexpression of both the MUC1 and FRA receptors on the breast cancer highlight the potential application of the radiolabeled MUC1-conjugated folate hybrid peptide as dual-receptor-targeting imaging probes for breast carcinoma imaging." (PMID 33738611, 2021). "MUC1 protein can attach to intercellular adhesion molecule-1 (ICAM-1), which promotes breast cancer cells adhesion to endothelial cells, leading to adhesion and consequent migration through the vessel wall." (PMID 34681197, 2021). "Next, Kaplan-Meier plotter was employed to assess the prognostic roles of MUC1, MUC15, MUC14 and MUC18 in breast cancer." (PMID 34828282, 2021). "The increased expression of MUC1 activates MAPK signaling through a physical interaction with ErbB1 and inhibition of ErbB1 degradation in breast cancer cells." (PMID 34681277, 2021). "Cell permeability inhibitors such as protein transduction domain MUC1 inhibitory peptide (PMIP), which interfere with MUC1-EGFR interactions, have been extensively developed and shown to effectively kill breast cancer cells both in vitro and in tumor models." (PMID 34207342, 2021). "Mucin 1 (MUC1) is a cell surface glycoprotein and expressed in over 90% of all breast cancers and 94% of the TNBC subtype." (PMID 33986665, 2021). "For instance, it has been shown that recruiting the AS1411 and mucin-1 (MUC-1) as conventional targeting aptamers on the surface of MSNs can significantly increase selective delivery of DOX and strong toxicity against MCF-7 breast cancer cells." (PMID 34641857, 2021).